HBB (hemoglobin subunit beta)
Diseases named in the same sentence as HBB in open-access papers (continued):
Sharing a sentence is not in itself a finding about the gene and the disease.
colorectal adenoma (1 paper, 2023). An adenoma that arises from the colon or rectum. "Our results provide the rationale to explore the role of HBB in colorectal adenoma development and the mechanism of Aspirin modulation." (PMID 37173923, 2023). "Proteomics of colorectal adenomas of FAP patients showed that the vimentin upregulation and hemoglobin subunit beta downregulation distinguished the FAP patients in two groups with high vs. low residual 11-dehydro-TXB2 levels, possibly identifying Aspirin nonresponders and responders, respectively." (PMID 37173923, 2023).
Duchenne muscular dystrophy (1 paper, 2022). Duchenne muscular dystrophy (DMD) is a neuromuscular disease characterized by rapidly progressive muscle weakness and wasting due to degeneration of skeletal, smooth and cardiac muscle. "We examined four more loci, including Duchenne muscular dystrophy (DMD) exon 53 and DMD exon 44 (537 kb away from each other), the 5′ coding region of HBB and an intergenic locus intragenic 1 (GRCh38.p13, chromosome 20, 32752960–32752979)." (PMID 35323942, 2022).
endometriosis (1 paper, 2024). The growth of functional endometrial tissue in anatomic sites outside the uterine body. "In the high JUP group, we identified several downregulated genes in the PBMCs from endometriosis patients, including HBB, HBA1, HBA2, RGPD2, CH25H, LTB, IFIT2 and JUN." (PMID 39684780, 2024). "Comparison between participants without endometriosis (n = 5) and participants with endometriosis (n = 4) with high serum JUP values (>220 ng/mL) identified nine DEGs (HBB, HBA1, HBA2, and RGPD2 in CD14+ monocytes; CH25H, HBB, LTB, and KLRC1 in γδt; IFIT2 in NK-CD56bright and JUN in Treg)." (PMID 39684780, 2024).
familial erythrocytosis (1 paper, 2022). "A review of the literature on recently reported mutations in patients with non-MPN erythrocytosis, highlighted the role of some known genes associated with familial erythrocytosis, such as EPO, HBB, VHL EGLN1, EPAS1, and EPOR." (PMID 36290845, 2022).
hepatitis B virus infection (1 paper, 2025). A viral infection caused by the hepatitis B virus. "Additionally, pathogenic HBB variants associated with hepatitis B virus infection, specifically c.126_129del (p.Phe42Leufs*19) and c.316–197C>T (p.)?" (PMID 40421383, 2025).
male infertility (1 paper, 2024). The inability of the male to effect fertilization of an ovum after a specified period of unprotected intercourse. "Furthermore, the ICSI-associated DEGs MAP1B, HBA1, EPHX1, HBB, and HBG2 enriched in response-to-toxic-substance pathway are also interesting (FDR-corrected q-value < 0.05), considering that environmental exposures have been associated with male infertility in previous studies." (PMID 39702541, 2024).
meningitis (1 paper, 2022). A disorder characterized by acute inflammation of the meninges of the brain and/or spinal cord. "However, we found a decreased expression of HBB in the saliva of pigs with meningitis, and a decreased level of this protein has been reported in the saliva of other animal species, like horses with acute abdominal disease." (PMID 36430174, 2022). "Among the proteins with the lowest FC in the saliva of piglets with meningitis, OBP2B and HBB might be the most relevant." (PMID 36430174, 2022).
multiple system atrophy (1 paper, 2017). Multiple system atrophy (MSA) is a neurodegenerative disorder characterized by autonomic failure (cardiovascular and/or urinary), parkinsonism, cerebellar impairment and corticospinal signs with a median survival of 6-9 years. "In addition to PD, altered expression of hemoglobin genes, including HBB, HBA1, and HBA2 have been found in the frontal cortex of multiple system atrophy patients, an atypical parkinsonian disorder that is often misdiagnosed as PD." (PMID 28424608, 2017).
non-small cell lung carcinoma (1 paper, 2021). A group of at least three distinct histological types of lung cancer, including non-small cell squamous cell carcinoma, adenocarcinoma, and large cell carcinoma. "In addition, the upregulation of HBB promotes epithelial–mesenchymal transition and has been commonly observed in circulating tumor cells of breast, prostate and non-small cell lung cancer patient-derived xenograft models." (PMID 34578801, 2021).
osteosarcoma (1 paper, 2024). A usually aggressive malignant bone-forming mesenchymal neoplasm, predominantly affecting adolescents and young adults. "Similarly, HBA1, HBA2, and HBB were downregulated in osteosarcoma samples." (PMID 38966281, 2024). "IFITM5, MMP13, PANX3, and MAGEA6 were some of the most overexpressed genes in osteosarcoma samples, while SLC4A1, HBA1, HBB, AQP7 genes were some of the top downregulated genes." (PMID 38966281, 2024).
pancreatic diseases (1 paper, 2021). "Some of them were upregulated in patients with other pancreatic diseases, such as HBB, HBA1, and KRT16 proteins, while some were upregulated only in PC groups (i.e. ALIX, GPRC5B, SDCBP, and IST1), highlighting their potential diagnostic value." (PMID 34026608, 2021).
pinguecula (1 paper, 2021). A yellowish thickened lesion on the conjunctiva near the cornea representing a benign degenerative change in the conjunctiva caused by the leakage and deposition of certain blood proteins through the permeable capillaries near the limbus. "For example, hemoglobin genes HBA1, HBA2, and HBB were among the top 25 upregulated genes in pinguecula and top 25 downregulated genes in pterygium." (PMID 34769520, 2021). "In this study, HBA1, HBA2, and HBB were among the top 25 upregulated DEGs in pinguecula and top 25 downregulated DEGs in pterygium." (PMID 34769520, 2021).
pneumonia (1 paper, 2025). An acute, acute and chronic, or chronic inflammation focally or diffusely affecting the lung parenchyma, caused by an infection in one or both of the lungs (by bacteria, viruses, fungi, or mycoplasma.). "For instance, a GWAS investigating pneumonia susceptibility and severity demonstrated a significant impact of the rs334 locus within the HBB gene." (PMID 39358504, 2025).
prion disease (1 paper, 2018). A transmissible disease that is caused by a protein that is able to induce abnormal folding of normal cellular proteins, leading to characteristic spongiform brain changes, which are associated with neuronal loss without an inflammatory response. "However, the analysis of HBB and HBA1/2 mRNA levels in acquired prion diseases patients revealed some differences, suggesting that exogenous prions might exert an impact on Hb metabolism." (PMID 29403351, 2018).
prostate tumours (1 paper, 2017). "Indeed, HBB mRNA level in primary tumour samples is generally low (0–0.9%), while increased expression is detected in 7 out of 19 metastatic prostate tumours (6.3–18.1%) (P=0.042)." (PMID 28181495, 2017).
renal carcinoma (1 paper, 2024). A carcinoma arising from the epithelium of the renal parenchyma or the renal pelvis. "For instance, genes such as MYBL2, C7, FAM111B, LYVE, PKMYT, and HBB display comparable importance in classifying both breast and renal carcinomas." (PMID 39596491, 2024).
renal cell carcinoma (1 paper, 2023). "However, the relationship between HBB expression and the prognosis of renal cell carcinoma (RCC) remains unclear." (PMID 37239002, 2023).
steatosis (1 paper, 2021). Increased lipid within the cytoplasm of cells. "Four genes had lower expression in steatosis (ABCA1, MTR, MTHFR, and PLG) and five genes had higher expression (SEPHS2, DIO1, HBB, SAA1, and SAA2) in the “selenoprotein micronutrient network” pathway." (PMID 34869521, 2021).
type 2 diabetes (1 paper, 2022). "Using pharmacophore target analysis in a network pharmacology approach, we identified five potential target genes for celastrol in the treatment of type 2 diabetes, including RBP3, BMP7, S100A11, HBB and IQUB." (PMID 36339449, 2022).
tumor (36 papers, 2014 to 2025). "Tumor cells expressing the Erythroid-like signature in patients 2 and 5 expressed early-stage erythroblast markers, but had lower expression of mid and late stage erythroid markers HBG1, HBG2, HBA2, and HBB than tumor-associated erythroid cells." (PMID 36008377, 2022). "Similarly, HBB, primarily known for its role in hemoglobin synthesis, has been implicated in tumor growth and metastasis in other cancer types." (PMID 40462176, 2025). "Validation using Western blotting analysis on 13 patients with type I EC at tumour stage 1 and 13 endometria samples confirmed the altered abundance of HBB, CKB, LDHB, and HSPB1." (PMID 37569364, 2023). "One tumor-associated cluster (HBB+/ALAS2+) expressed high levels of erythroid progenitor genes (KLF1) and was highly proliferative, which we annotated as tumor-associated erythroid cells." (PMID 36008377, 2022). "Authors suggested a positive correlation between HBB expression and ability of disseminating tumor cells in other organs, indicating a more aggressive phenotype." (PMID 34320944, 2021). "Chemoresistant tumor cells were detected in lungs of these seven animals by qPCR as molecular analysis confirmed human HBB specific sequences in all animals in contrast to no presence of human sequences in mice (n = 7) injected with HT-29/EGFP cells." (PMID 30143021, 2018). "The composite meta-score demonstrates elevated expression of HBB in metastatic tumours compared with primary tumours (P=0.019), with 6 out of 19 datasets exhibiting a positive score with a significant P value." (PMID 28181495, 2017). "Although levels of HBB expression in primary tumour specimens are much lower than in CTCs, detection of HBB mRNA in human tumour specimens is correlated with adverse clinical outcomes." (PMID 28181495, 2017). "Expression of HBB is low in primary tumour cells, markedly induced in CTCs, and then again reduced in metastases." (PMID 28181495, 2017). "By comparing single-cell transcriptome profiles of CTCs from multiple different human cancers, we identify β-globin (HBB) as one of the transcripts most consistently overexpressed in these tumour-derived cells." (PMID 28181495, 2017). "Conversely, depletion of HBB in cancer cells enhances their sensitivity to ROS and abrogates their ability to form anchorage-independent colonies, a marker of tumour progenitor capacity." (PMID 28181495, 2017). "To identify candidate regulators of HBB induction in tumour cells, we first screened for transcription factors and chromatin regulators whose expression is positively correlated with HBB levels in multiple expression datasets of human cancer." (PMID 28181495, 2017). "Our results suggest that PDE3B and HBB may modulate the immune microenvironment, potentially contributing to tumor immune evasion and progression." (PMID 40462176, 2025). "While HBB expression is comparably low in primary tumours, we used multiple primary datasets to test whether any baseline HBB expression in primary tumours from multiple tissue types is correlated with patient outcome." (PMID 28181495, 2017). "While such simultaneous comparisons of primary tumour, CTCs and metastatic tumours are challenging in clinical cohorts, we tested for a correlation between HBB expression in CTCs and tumour progression in a cohort of patients with advanced castration-resistant prostate cancer (CRPC)." (PMID 28181495, 2017). "Expression of HBB was significantly elevated in >50% of CTCs from breast, prostate and lung cancers (Reads Per Million: RPMmedian=3,630, range (1.6–894,101); P=2.59E–07 for CTCs versus primary tumour and cancer cell lines)." (PMID 28181495, 2017). "Notably, several upregulated genes, including PDE3B and HBB, overlapped with malignant cell type-specific markers, suggesting these genes may play roles in tumor progression and proliferation." (PMID 40462176, 2025).
tumor (continued). "Our findings shed light on the molecular mechanisms driving tumor progression and highlight PDE3B and HBB as promising therapeutic targets." (PMID 40462176, 2025). "WB analysis of serum and tumor tissue specimens confirmed the upregulation of eight proteins: APOA1, HBB, CAH1, HBD, LPA, SAA4, PF4V1, and APOE." (PMID 39194522, 2024). "The genes with the highest log fold-change of expression in the tumor chunks compared to the dissociated cells were hemoglobin genes (HBA1, HBA2, HBB)." (PMID 37864274, 2023). "In contrast, the C3 subpopulation, enriched in genes like HBB and JUNB, may contribute to oxidative stress regulation and cell cycle progression, suggesting a more mature, functionally active tumor cell." (PMID 40406148, 2025). "Furthermore, when comparing T cells from BM with those from primary tumor IV, we observed significant alterations in the expression of genes such as PLP1 (log2FC = 2.34), HSPA1A (log2FC = 2.09), HBB (log2FC = −2.93), and HBA2 (log2FC = −2.44)." (PMID 38612588, 2024). "Interestingly, the high abundance identifies were consistent both in the tumor and normal tissues in EESCC and EDAC at the protein level, including HBB, HBA1, HBD, ACTB, ALB, etc.." (PMID 35397555, 2022). "None of these were seen in the central part of the tumor where two other spots were detected, spot 3203 and HBB (spot 7106)." (PMID 34563043, 2021). "Unexpectedly, a haemoglobin gene, HBB (encoding β-globin), but not its binding partner HBA (encoding α-globin), was significantly overexpressed in CTCs across all three tumour types." (PMID 28181495, 2017). "Decorin, mimecan, hemoglobin subunit alpha, hemoglobin subunit beta, and keratin type I cytoskeletal 19 were upregulated in normal tissue, whereas periostin and versican core protein were upregulated in phyllodes tumor tissue." (PMID 25400079, 2014). "In their study, samples from three groups (PA, residual PA, and CXPA) were analyzed to identify protein signatures and their results suggested that seven proteins (APOA1, AP1M1, SYCP1, DCD, HBB, HP, and SLC4A1) could be potential signatures for tumor progression or suppression." (PMID 39155517, 2025). "Moreover, both genes appear to modulate the tumor immune microenvironment, suggesting that combining PDE3B or HBB inhibition with immune checkpoint blockade may yield synergistic antitumor effects." (PMID 40462176, 2025). "Because both cancer cohorts have no HGB-related clinical data available, we quantified a tumor’s HGB level as the average expression levels of four HGB-related genes (HBA1, HBA2, HBB and HBD)." (PMID 39415833, 2024). "Hemoglobin subunit beta (HBB) and hemoglobin subunit alpha 1 (HBA1) mRNA levels were significantly upregulated in MBM, although their upregulation in MBM may reflect a hemorrhagic component of the tumor as opposed to a true biological difference." (PMID 37964004, 2023).
cancer (27 papers, 2013 to 2025). A tumor composed of atypical neoplastic, often pleomorphic cells that invade other tissues. "In the field of cancer research, an overexpression of hemoglobin subunit beta has been associated with an increase in the level of neoangiogenesis." (PMID 35292718, 2022). "We performed fine-mapping of the HBB locus and assessed the germline for cancer predisposition genes." (PMID 34261517, 2021). "Cancer progression has been linked to the involvement of Beta-globin (HBB) in various pathways." (PMID 39355132, 2024). "Hemoglobin subunit beta has also been reported to be a diagnostic biomarker in cancers." (PMID 34458266, 2021). "The cancer progenitor cells had both mature cell features, for example, HBB expression, and early progenitor properties, for example, proliferative phenotype." (PMID 38649187, 2024). "In this regard, HBA1 and HBB present challenging candidates for ROS-targeted cancer therapy due to their known expression in erythrocyte tissues." (PMID 38067210, 2023). "The LC-LK CCPs are made of two or three nodes maximum and identified four genes (SNRK, BIRC5, HBB, and IL33) associated with the acquisition of the hallmarks of cancer." (PMID 36101460, 2022). "ReactomeFIViz enrichment analysis in Cytoscape showed that four genes (SNRK, BIRC5, HBB, and IL33) have evidence of their association with the acquisition of cancer characteristics." (PMID 36101460, 2022). "Among significantly positive miRNA-mRNA pairs correlation covering at least 10 cancer types, 2 pairs from our list can be found: hsa-miR-486-5p~HBB and hsa-miR-223-3p~HBEGF." (PMID 34320033, 2021). "ISH images showed the HBB mRNA expression was localized mostly within the cytoplasm of cancer cells while only a small amount of expression was observed in non-cancerous tissues." (PMID 24489662, 2014). "A deeper examination of the feature importance of the cancer detection model has revealed the top five transcripts at play: FKBP5, TMSB4XP8, MTRNR2L12, HBB, and SPDYC." (PMID 38887841, 2024). "The exploration of the feature importance of the cancer detection model has pinpointed the top five transcripts characterized by their largest weight on prediction outcomes: FKBP5, TMSB4XP8, MTRNR2L12, HBB, and SPDYC." (PMID 38887841, 2024). "HBB and HBA1 are now anti-metastatic factors in other cancers and the downregulation of these genes may be indicative for enhanced formation of metastases." (PMID 38966281, 2024). "Given that the immunohistochemistry employed here only detects HBB at the protein level, positive staining does not exclude the possibility of Hb uptake by cancer cells from the surrounding tissues." (PMID 24489662, 2014). "First of all, in analyzing the TCGA and Pancancer_2020 cohorts, we have used the mean expression levels of HBA1, HBA2, HBB and HBD to represent HGB levels of cancer patients, which may not fully reflect blood HGB levels." (PMID 39415833, 2024).
blood disorder (20 papers, 2007 to 2025). "Beta-thalassemia is a hematopoietic disease caused by a single-gene mutation of the hemoglobin (HGB) subunit beta gene (HBB), leading to anomalous beta-globin expression." (PMID 35682629, 2022). "β-Thalassemia is an inherited hematological disorder caused by mutations in the human hemoglobin beta (HBB) gene that reduce or abrogate β-globin expression." (PMID 30430274, 2018). "Although β-Thalassemia is a common blood disorder, HBB gene had a lower number of variants than expected, this can be explained by the design of the panel, which doesn’t cover deep intronic, UTR and copy number variants, these are common types of causative mutations in β-Thalassemia32–34." (PMID 34272389, 2021). "However, HBB deficiency is related to hematological disorders such as β-Thalassemia." (PMID 39237431, 2024). "β-thalassemia is an inherited blood disorder caused by mutations in the β-globin (HBB) gene, leading to reduced or absent β-globin production, resulting in chronic anemia." (PMID 41148810, 2025). "β-thalassemia is a hereditary hematological disorder caused by mutations in the β-globin gene (HBB), leading to deficient or absent production of β-globin chains." (PMID 41148810, 2025). "HBB c.-29G>A appeared to be one of the first examples of uAUG-creating variants associated with tan inherited blood disorder, β-thalassemia characterized by marked reduce or absence of the beta-chain of hemoglobins." (PMID 35387445, 2022). "As a first target for this method, we chose two sites: a 6-bp region spanning three codons within the human hemoglobin subunit beta (HBB) gene that is of great importance for adaptation and hematologic disease, and the identical, paralogous region within the hemoglobin subunit delta (HBD) gene." (PMID 35031571, 2022). "The β-thalassemias (OMIM #613985) are a group of inborn blood disorders characterized by reduced or absent beta hemoglobin chains due to mutations in the HBB gene." (PMID 36499615, 2022). "Haematological disorders have been frequently noticed as secondary findings, including G6PD (NM_000402.3):c.653C>T (OMIM 300908), HBB (OMIM:613985) and (OMIM: 603903)." (PMID 37799141, 2023).